TLR1 (toll like receptor 1)
Diseases named in the same sentence as TLR1 in open-access papers (continued):
Sharing a sentence is not in itself a finding about the gene and the disease.
astrocytoma (2 papers, 2018 to 2023). "This study aims to analyze the expression levels of plasmatic cell membrane TLRs (TLR1, TLR2, TLR4, TLR5, and TLR6) in human astrocytomas the most prevalent tumors of CNS different grades (II-IV)." (PMID 29912993, 2018). "Genes coding the five receptors, TLR1, 2, 4, 5, and 6, presented higher expression levels in astrocytoma samples compared to non-neoplastic brain tissues, with statistical significance (p < 0.05)." (PMID 29912993, 2018). "TLR1, TLR2, TLR4, TLR5, and TLR6 are involved in a diversity of cellular responses, ranging from cell proliferation to cell death, and as such they are the targets of the current study in astrocytomas." (PMID 29912993, 2018). "In this regard, experimental evidence on the increased cell surface expression of TLR1, TLR2, TLR4, TLR5, and TLR6 in astrocytoma samples compared to non-neoplastic brain tissues clearly revealed the involvement of these TLRs in the progression of astrocytoma." (PMID 37822929, 2023). "In summary, increased cell membrane TLR1, TLR2, TLR4, TLR5, and TLR6 expressions were demonstrated in astrocytomas compared to non-neoplastic brain tissue, mostly in GBM group, and particularly in the mesenchymal subtype." (PMID 29912993, 2018). "In the present study, higher expression levels of TLR1, TLR2, TLR4, TLR5, and TLR6 were demonstrated in human diffusely infiltrating astrocytomas (grades II to IV) in comparison to non-neoplastic brain tissue." (PMID 29912993, 2018).
B cell lymphoma (2 papers, 2015 to 2025). "For instance, for B cell lymphoma, the TLR1/2 agonist (Pam3CSK4) was applied with the conventional chemotherapeutic agent Ara-C, resulting in a synergistic anticancer effect through the up-regulation of immunomodulatory molecules." (PMID 25887995, 2015). "On the contrary, consistent with the findings of this study, Pam3CSK4 synergized with Ara-C in killing B cell lymphoma cells and it triggered apoptosis of acute myeloid leukemia (AML) cells indicating possible context-dependent activation effects of TLR1/2 activation." (PMID 39874349, 2025).
breast tumor (2 papers, 2019 to 2021). "breast tumor myeloid cells, the expression of 5 TLR genes (TLR1, TLR2, TLR4, TLR7 and TLR8) were detected in >10% of cells and at moderate to high expression levels." (PMID 34956864, 2021).
brucellosis (2 papers, 2020 to 2025). Brucellosis is a bacterial infection that spreads from animals to people via unpasteurized dairy products or by exposure to contaminated animal products or infected animals. "Tlr1 heterozygous status was also associated with ibex brucellosis status but this most likely result from the systematic presence of the Tlr1b haplotype in Tlr1 heterozygous ibex." (PMID 32157133, 2020).
C. perfringens infection (2 papers, 2021 to 2022). "However, the increased mRNA expression (TLR1 and TLR2) caused by C. perfringens infection was effectively inhibited (p < 0.01) by co-incubation with L. plantarum Lac16." (PMID 34830269, 2021). "Docking was performed against TLR1/TLR2 and TLR4/MD2, as they have been widely reported to be important in the innate defense against C. perfringens infection in chickens and mice, although little is known in humans." (PMID 36110855, 2022).
colon carcinoma (2 papers, 2023 to 2024). "Taken together, our studies showed that the TLR1-N248S polymorphism is not only a prognostic but also a predictive factor for the clinical response to adjuvant chemotherapy in patients with locally advanced colon carcinoma." (PMID 37945630, 2023). "In this study, we investigated the impact of genetic variation in TLR1 and TLR2, which are the receptors for HMGB1, on the clinical outcomes of colon carcinoma (COAD) patients who underwent postoperative adjuvant chemotherapy, specifically those with regional lymph node metastatic COAD." (PMID 37945630, 2023). "Overall, our results suggest that dysfunctional TLR1 may reduce the therapeutic response to adjuvant chemotherapy by impairing HMGB1-mediated DC maturation and attenuating the antitumor immune response in locally advanced colon carcinoma patients." (PMID 37945630, 2023).
Crohn disease (2 papers, 2020 to 2025). A gastrointestinal disorder characterized by chronic inflammation involving all layers of the intestinal wall, noncaseating granulomas affecting the intestinal wall and regional lymph nodes, and transmural fibrosis. "Accumulating evidence suggests that vitamin D beneficially reduced TLR1 and NOD1 in Crohn’s disease." (PMID 40723565, 2025).
dengue (2 papers, 2008 to 2021). "In a previous study, a differentially expressed TLR profile was reported in children with severe dengue, wherein increased expression of TLR7 and TLR4 transcript variant 3 (TLR4R3) and decreased expression of TLR1, TLR2, TLR4R4, and TLR4 cofactor CD14 were observed." (PMID 34603272, 2021).
disc degeneration (2 papers, 2021 to 2023). "In human IVD’s there is expression of TLR-1, 2, 3, 4, 5, 6, 9, and 10 and the expression of TLR-1, 2, 4, and 6 are increased with degree of disc degeneration and pain." (PMID 33863359, 2021). "In human IVD, there is an expression of Toll-like receptor (TLR)-1, -2, -3, -4, -5, -6, -9, and 10, and the expression of TLR-1, -2, -4, and -6 are increased with the degree of disc degeneration and pain." (PMID 37627322, 2023).
encephalitis (2 papers, 2022 to 2023). An acute inflammatory process affecting the brain parenchyma. "Proteomics analysis showed activation of inflammation pathways including JAK-STAT signaling, TLR1/TLR2 cascade, NFκB phosphorylation and IKK complex, as well as other innate immunity components that support the monocytic inflammation nature of the encephalitis." (PMID 36609561, 2023).
esophageal adenocarcinoma (2 papers, 2018 to 2025). A malignant tumor with glandular differentiation arising predominantly from Barrett mucosa in the lower third of the esophagus. "For example, in esophageal cancer, increased expression of TLR3, TLR4, TLR7, and TLR9 has been linked to esophageal squamous cell carcinomas, while TLR1, TLR2, TLR4, and TLR6 are often overexpressed in esophageal adenocarcinoma." (PMID 40109582, 2025). "The concept of a universal role for TLR1 in tumor regression is however undermined by data suggesting that it may promote esophageal adenocarcinoma." (PMID 29416610, 2018).
hepatitis C (2 papers, 2011 to 2014). "Specific activation of TLR-2 in hepatitis C and homo- or heterodimerization with TLR-1 or TLR-6 has been shown; also, when these are blocked a significant decrease on production of proinflammatory cytokines appears, suggesting that some proteins produced by hepatitis C activate innate immune." (PMID 22114589, 2011).
HIV-1 infection (2 papers, 2019 to 2023). The type species of lentivirus and the etiologic agent of acquired immunodeficiency syndrome (AIDS). "For this purpose, HIV-1 reporter TZMbl cells were transiently transfected alone or in combination with plasmids overexpressing TLR10 and the heterodimers, TLR2 and TLR1, followed by HIV-1 infection and measurement of luciferase activity." (PMID 30930906, 2019). "In addition, HIV-1 infection was significantly elevated in TZMbl cells, which were either co-transfected with TLR1/10 or TLR2/10 compared to the control (P < 0.05)." (PMID 30930906, 2019). "In order to observe the HIV-1 infection in susceptible cells, macrophages were differentiated from THP-1 cells to determine whether siRNA-mediated knockdown of TLR1, 2 and/or 10 for 2 days prior to CCR5-tropic HIV-1 (BAL strain) exposure for 7 days would affect the HIV-1 infection rate." (PMID 30930906, 2019). "We suggest that TLR10 and TLR1 both work cooperatively as the transfection of TRL10 and TLR1 alone or in combination significantly enhanced HIV-1 infection, indicating that TLR10 and TLR1 likely form heterodimers." (PMID 30930906, 2019). "The results showed a significantly increased rate of HIV-1 infection in TZMbl cells overexpressing TLR10 and heterodimers TLR1 or TLR2 compared to the empty vector alone, uninfected control or a T20 control (Enfuvirtide; HIV-1 fusion inhibitor) (P < 0.05)." (PMID 30930906, 2019). "Together, these data indicate that the expression of TLR1, 2 and TLR10 alone or in combination significantly enhances HIV-1 infection and integration in vitro." (PMID 30930906, 2019). "Given that TLR10 is a homolog of both TLR2 and TLR1, we hypothesized that TLR10 is involved in sensing specific HIV-1 structural proteins, which leads to increased cellular activation and HIV-1 infection." (PMID 30930906, 2019). "Surprisingly, with the exception of TLR1 and TLR2, we found significantly higher levels of TLR10 (>100-fold) expression in BM samples collected from HIV-1 infected Nigerian women, thus indicating that TLR10 might play an important role in HIV-1 infection and pathogenesis." (PMID 30930906, 2019). "Thus, we assessed inflammasome activation by HIV-1 infection or VbP treatment with and without pretreating THP-1 cells with agonists of TLR1/2 (Pam3CSK4), TLR7/8 (CL075), TLR8 (TL8-506), or TLR4 (LPS)." (PMID 37417868, 2023).
insulin-dependent diabetes mellitus (2 papers, 2018 to 2024). "Two TLR1 (OMIM 601194) or Toll-like receptor (TLR) on 4p14 and SELL (OMIM 153240) or L-Selectin on chromosome 1q24.2 are candidate genes for the development of type 1 diabetes." (PMID 30212560, 2018).
lepromatous leprosy (2 papers, 2008 to 2024). A chronic communicable infection which is a principal or polar form of leprosy. "An association of 1805G with lepromatous leprosy could explain the intriguing earlier observation by Krutzik and coworkers, who examined TT and LL lesions and were unable to detect any TLR1 staining in LL lesions." (PMID 18461142, 2008). "Collectively, these findings suggest that TLR1 biology is different in lepromatous leprosy than in other forms of the disease." (PMID 18461142, 2008). "(2003) identified that TLR1 and TLR2 are expressed in greater amounts in individuals with tuberculoid leprosy than in patients with lepromatous leprosy." (PMID 39308868, 2024).
lupus (2 papers, 2018 to 2020). "Exosomes derived from lymphocytic leukemia (CLL) can target TLR7 signaling to promote innate immunity, while exosomes isolated from systemic lupus erythematosus (SLE) patients' serum can produce abundant IFN-α, TNF-α, IL-1β, and IL-6 via the TLR1/2, TLR7, TLR9, and TLR4 pathways." (PMID 32565722, 2020).
lymph node metastases (2 papers, 2023 to 2024). "Of the 95 lymph node metastases, analyzable samples were available for 70 (TLR1), 72 (TLR2), 77 (TLR4), 58 (TLR5), 76 (TLR6), 72 (TLR7), 76 (TLR8) and 70 (TLR9) cases." (PMID 38709790, 2024). "Our data showed for the first time that TLR1-N248S was associated with the clinical outcome of patients with locally advanced stage III COAD, suggesting that this genetic defect might be associated with the risk of lymph node metastasis and poor DMFS." (PMID 37945630, 2023).
lymphoma (2 papers, 2016 to 2024). A malignant (clonal) proliferation of B- lymphocytes or T- lymphocytes which involves the lymph nodes, bone marrow and/or extranodal sites. "For example, TLR1 SNP associated with lymphoma can indicate enhanced susceptibility to Helicobacter pylori infection in lymphoma patients." (PMID 39403369, 2024). "The identification of microbial and/or endogenous ligands for TLR1/2 or TLR5 may provide new therapeutic targets to be exploited to counteract the tumor promoting effects of lymphoma microenvironment." (PMID 27123851, 2016).
myocardial infarction (2 papers, 2018 to 2019). Gross necrosis of the myocardium, as a result of interruption of the blood supply to the area, as in coronary thrombosis. "To reveal changes in Tlr mRNA expression caused by myocardial ischaemia, we examined mRNAs for Tlr1‐9 in a murine myocardial infarction model, and in cultured H9c2 myocytes and NRVMs exposed to ischaemia." (PMID 31517441, 2019). "In this study, we observed highly increased gene expression levels of Tlr1, Tlr2, Tlr6, Tlr7, Tlr8, Tlr9 as well as Irf7 in the scar tissue after myocardial infarction, indicating their relevance to a proper cardiac wound healing." (PMID 29538462, 2018).
otitis (2 papers, 2021 to 2025). "In another study, in which OME children who had undergone ventilation tube insertion were classified into otitis-prone and non-otitis-prone groups, a comparison of TLR1 expression in middle ear effusion of both groups showed a trend toward higher expression of TLR1 mRNA in the otitis-prone group." (PMID 34360632, 2021). "TLR-1, -2, -4, -5, -6, -9; IL-6, -8, -10, -12; IFN-γ; TNF-α; and NOS mRNA expression was measured in effusions from both otitis-prone and non-otitis-prone groups." (PMID 40227356, 2025).
ovarian carcinoma (2 papers, 2021 to 2024). A malignant neoplasm originating from the surface ovarian epithelium. "Our results support the idea that a panel of tumor-related proteins, including heterogeneously expressed proteins such as renin, ACVR1, TLR1, and KLKs,5,7,11 may encompass tumor heterogeneity in ovarian cancer patients." (PMID 34868557, 2021).
pancreatic ductal adenocarcinoma (2 papers, 2021 to 2022). An infiltrating adenocarcinoma that arises from the epithelial cells of the pancreas. "Higher TLR1 expression suggested better prognosis in patients with pancreatic ductal adenocarcinoma (PDAC)." (PMID 34407874, 2021). "In pancreatic ductal carcinoma, the strong expression of TLR1 indicates a good prognosis, while the negative expression of TLR1 is a sign of poor prognosis." (PMID 36171883, 2022).
parasitemia (2 papers, 2017 to 2020). "iRBC- and TLR1/2 and TLR4 agonist-induced CD86 expression was also lower in CD1c+ cells isolated at peak parasitemia than prior to infection, while there was no change in TLR1/2 and TLR4-induced IL-12 expression and all three stimuli, iRBCs, TLR1/2 and TLR4 agonists, increased intracellular TNF." (PMID 31900030, 2020).
Parkinson disease (2 papers, 2023 to 2025). A progressive degenerative disorder of the central nervous system characterized by loss of dopamine producing neurons in the substantia nigra and the presence of Lewy bodies in the substantia nigra and locus coeruleus. "Extracellular α-synuclein is a key driver of Parkinson’s disease that binds TLR1/2 on microglia, activating the TAM-family kinases Mer and." (PMID 41236793, 2025). "SNPs including TLR1 rs4833095, TLR2 rs3804099 and TLR4 rs1927914 were associated with increased risk of Parkinson’s disease (PD)." (PMID 37191444, 2023).
pulmonary diseases (2 papers, 2005 to 2022). "This raises questions about the effect of increased TLR1 expression in enhancing severe pulmonary diseases." (PMID 36611413, 2022).
pyelonephritis (2 papers, 2009 to 2015). An inflammatory process affecting the kidney. "Polymorphism TLR1_G1805T was associated with protection from pyelonephritis (OR(95%CI): 0.53 (0.29–0.96))." (PMID 19543401, 2009).
adenomyosis (1 paper, 2017). The growth of endometrial tissue inside the muscular wall of the uterine corpus. "In addition, we analyzed the correlation between IL-6 and IL-8 and TLRs in adenomyosis patients and found that TLRs were positively correlated with corresponding IL-6 and IL-8 in EU and EC, of which TLR1, 2, 4, 5 and 9 were significantly positively correlated with IL-6 and IL-8." (PMID 28779087, 2017).
adult-onset Still disease (1 paper, 2022). A rare inflammatory multisystem disorder characterized clinically by fever of unknown origin, arthralgia or arthritis, hyperleucocytosis, and typical skin rash. "This study investigated the role of Toll-like receptor 1 (TLR1), TLR2, TLR4, TLR7, and TLR9 in patients with adult-onset Still’s disease (AOSD)." (PMID 35715478, 2022).
alcoholism (1 paper, 2018). "We identified that alcoholism and the TLR1 1805G allele may be predictive variables for multibacillary TB." (PMID 29988507, 2018).
amyotrophic lateral sclerosis (1 paper, 2022). Amyotrophic lateral sclerosis (ALS) is a neurodegenerative disease characterized by progressive muscular paralysis reflecting degeneration of motor neurons in the primary motor cortex, corticospinal tracts, brainstem and spinal cord. "Although the role of TLR1 in neurodegenerative diseases is not yet clear, TLR2 involvement in microglial activation has been increasingly demonstrated in amyotrophic lateral sclerosis, MS, and AD." (PMID 35408945, 2022).
anemia (1 paper, 2018). A reduction in the number of red blood cells, the amount of hemoglobin, and/or the volume of packed red blood cells. "In summary, anemia in infancy was associated with reduced pro-inflammatory cytokine response to TLR1-2 and TLR4 stimulation, as well an increased prevalence of nasopharyngeal colonization with M. catarrhalis." (PMID 29559671, 2018). "Results from current study showed that infant anemia was associated with decreased pro-inflammatory cytokine responses to TLR1-2 and TLR4 stimulation, as well an increased prevalence of nasopharyngeal colonization with M. catarrhalis." (PMID 29559671, 2018).
Anxiety (1 paper, 2025). Intense feelings of nervousness, tension, or panic often arise in response to interpersonal stresses. "In our study, the increased expression levels of Tlr1/2 were also observed in Asm KO mice, indicating an association between activated Tlr1/2 and the anxiety-like behavior in Asm KO mice." (PMID 39905541, 2025). "To further validated the downstream impacts of Tlr1/2 activation on immune cells in Asm KO induced anxiety, we assessed the expression of iba-1, a marker of microglial activation, and observed an increased number of microglia with the activated morphology." (PMID 39905541, 2025). "Female offspring of mice fed with 2.5 times the recommended amount of folic acid exhibited increased anxiety behaviors, accompanied by an increase in Tlr1 mRNA expression levels in their brains." (PMID 39905541, 2025).
anxiety disorder (1 paper, 2025). A category of psychiatric disorders which are characterized by anxious feelings or fear often accompanied by physical symptoms associated with anxiety. "Thus, Tlr1/2 could be the crucial inflammatory mediators in anxiety disorder." (PMID 39905541, 2025).
aortic valve disease (1 paper, 2025). "The present study builds upon our previous findings in heart tissue from patients with advanced coronary artery disease and aortic valve disease, which demonstrated increased expression of TLR1, TLR3, and TLR7, along with elevated levels of their downstream signaling mediators." (PMID 39828779, 2025).
bacteremia (1 paper, 2024). "We have previously reported associations of TLR1 single nucleotide missense variant rs76600635 with mortality and of TLR5 nonsense variant rs5744168 with both bacteremia and mortality in single-center studies of patients with melioidosis in northeastern Thailand." (PMID 38507807, 2024). "We conclude that in a large multicenter cohort of patients hospitalized with melioidosis in northeastern Thailand, neither TLR1 missense variant rs76600635 nor TLR5 nonsense variant rs5744168 is associated with bacteremia or mortality." (PMID 38507807, 2024). "Therefore, in this study, we take advantage of a large prospective, multicenter observational study that recruited melioidosis patients hospitalized in northeastern Thailand to test the associations of TLR1 variant rs76600635 and TLR5 variant rs5744168 with bacteremia and mortality in melioidosis." (PMID 38507807, 2024).
Barrett’s metaplasia (1 paper, 2021). "In support of these findings, a recent report by Huhta and colleagues showed, using immunohistochemistry, that TLR1, 2 and 6 expression levels increased during Barrett’s metaplasia and dysplasia." (PMID 33922955, 2021).